LINC01559 (long independently transcribed non-coding RNA 1559)
Synonyms: C12orf36; FLJ33810
Gene: Long non-coding RNA gene on chromosome 12 (13,371,089 to 13,387,167, reverse strand). Ensembl gene ENSG00000180861.
Diseases named in the same sentence as LINC01559 in open-access papers:
LINC01559 is named in the same sentence as 19 diseases in open-access papers, as found by Europe PMC text mining. Sharing a sentence is not in itself a finding about the gene and the disease. The quoted sentences say what the papers report.
gastric cancer (6 papers, 2020 to 2024). A primary or metastatic malignant neoplasm involving the stomach. "LINC01559 is known to be transcriptionally upregulated by the transcription factor zinc finger E-box binding homeobox 1 (ZEB1) in gastric cancer." (PMID 38311781, 2024). "LINC01559 played an important role in gastrointestinal tumors such as pancreatic cancer, gastric cancer and liver cancer." (PMID 36248984, 2022). "Among the six selected ARlncRNAs, LINC01559 was reported to be upregulated in renal cell carcinoma, gastric cancer, PC, and hepatocellular carcinoma." (PMID 33384999, 2020). "Similarly, while LINC01559 has been reported to be transferred from mesenchymal stem cells (MSCs) into gastric cancer, whether this also occurs in the context of other types of cancers, including LUAD remains to be clarified." (PMID 38311781, 2024). "Recently, LINC01559 was found to recruit IGF2BP2 to stabilize ZEB1 expression and accelerate gastric cancer cell proliferation, migration and EMT." (PMID 35299748, 2022). "Similarly, LINC01559 can enhance the stability of ZEB1 mRNA by recruiting IGF2BP2, accelerate the proliferation and migration of gastric cancer cells, and promote the malignant development of gastric cancer." (PMID 38040698, 2023). "However, the expression level and function of LINC01559 (long intergenic non-protein coding RNA 1559) in gastric cancer (GC) are rarely reported." (PMID 32895368, 2020).
pancreatic cancer (6 papers, 2020 to 2024). "Moreover, LINC01559 has been shown to function as a competing endogenous RNA (ceRNA) of miR-1343-3p to accelerate triple-negative breast cancer progression, and similarly as a ceRNA to promote the progression of colorectal cancer and pancreatic cancer." (PMID 38311781, 2024). "We also identified that the low expression of MEG3, LINC01963, and LINC00261 and the high expression of MACC1-AS1, LINC00462, LINC01559, and UCA1 were significantly correlated with worse survival in pancreatic cancer patients." (PMID 34827663, 2021).
lung adenocarcinoma (3 papers, 2021 to 2025). A carcinoma that arises from the lung and is characterized by the presence of malignant glandular epithelial cells. "This study identifies LINC01559 as a novel ceRNA that drives osimertinib resistance in lung adenocarcinoma by sponging miR-320a to enhance IGF2BP3 expression." (PMID 40313617, 2025). "In order to explore the function of LINC01559, we transfected two lung adenocarcinoma cell lines with small interfering RNA." (PMID 34823534, 2021). "In vitro experiments demonstrated that the expression of LINC01559 was up-regulated in both lung adenocarcinoma cell lines A549 and H1299, and silenced LINC01559 can mitigate the proliferation, migration and anti-apoptotic ability of tumor cells in vitro." (PMID 34823534, 2021). "We then discussed how LINC01559 regulates autophagy in lung adenocarcinoma cells." (PMID 34823534, 2021).
hepatocellular carcinoma (2 papers, 2020). A malignant tumor that arises from hepatocytes. "Moreover, the LINC01559 can act as an potential oncogene, thereby accelerating the resistance of hepatocellular carcinoma to oxaliplatin by sponging miR-6783-3p." (PMID 33324563, 2020).
lung carcinoma (2 papers, 2021 to 2025). "To investigate the biological functions of LINC01559, we first analyzed its expression across lung cancer cell lines and normal bronchial epithelial cells." (PMID 40313617, 2025). "To validate LINC01559’s role in lung cancer, we established stable knockdown and overexpression in H1975 and PC-9 cells." (PMID 40313617, 2025). "Although lncRNAs play important role in regulating the autophagy of tumor cells, the function and molecular mechanism of LINC01559 in regulating lung cancer development remain to be elucidated." (PMID 34823534, 2021). "Besides, LINC01559 promotes lung cancer cell proliferation and migration in vitro, by enhancing autophagy signal pathway via sponging hsa-miR-1343-3p." (PMID 34823534, 2021).
lymph node metastasis (2 papers, 2020 to 2021). "High expression of LINC01559 was significantly associated with large tumors, lymph node metastasis, and poor prognosis." (PMID 32678071, 2020).
colorectal cancer (1 paper, 2024). A primary or metastatic malignant neoplasm that affects the colon or rectum. "Moreover, m6A RNA methylation of LINC01559 has also been reported to play a role in regulating its expression in colorectal cancer." (PMID 38311781, 2024).
duodenal adenocarcinoma (1 paper, 2025). A carcinoma that arises from glandular epithelial cells of the duodenum. "The results suggested that GRSF1 may play a tumor-promoting role in duodenal adenocarcinoma under acidic conditions and is regulated by Linc01559." (PMID 40722682, 2025). "Additionally, invasion and migration assays demonstrated that Linc01559 knockdown markedly inhibited the invasive and migratory capacities of duodenal adenocarcinoma cells." (PMID 40722682, 2025). "In summary, Linc01559 may influence the malignant phenotype of duodenal adenocarcinoma cells by regulating GRSF1 expression." (PMID 40722682, 2025).
duodenal cancer (1 paper, 2025). "It was further revealed that Linc01559 promotes the malignant phenotype of duodenal cancer cells through its interaction with GRSF1." (PMID 40722682, 2025). "High expression of Linc01559 and GRSF1 in duodenal cancer tissues indicates an increased risk of tumor recurrence and metastasis, suggesting that GRSF1 may represent a potential therapeutic target for duodenal cancer." (PMID 40722682, 2025).
tumor (10 papers, 2020 to 2025). "Moreover, we conducted loss-of function assays and found that silencing of LINC01559 obviously inhibited the growth and migration of GC cells, which suggested that LINC01559 could play a tumor promoting role in GC progression." (PMID 33824282, 2021). "Strikingly, combining LINC01559 knockdown with osimertinib (sh1-LINC01559 + Osimertinib) synergistically suppressed tumor progression, with tumors exhibiting smaller volumes and reduced weights." (PMID 40313617, 2025). "In our study, rescue experiments demonstrated that IGF2BP3 restoration reversed the tumor-suppressive effects of LINC01559 knockdown, confirming its functional indispensability in this axis." (PMID 40313617, 2025). "Subsequent validation via qPCR confirmed that Linc01559 was significantly upregulated in tumor tissues." (PMID 40722682, 2025). "It was found that HIF1α, STAT3, and MYC were highly expressed in tumor tissues and were positively correlated with Linc01559 expression (Figure A2a)." (PMID 40722682, 2025). "In conclusion, LINC01559 is expressed at low levels in CRC, and downregulated LINC01559 expression leads to poor prognosis, which indicates that LINC01559 is a tumor suppressor marker in CRC." (PMID 35541914, 2022). "As expected, silencing of LINC01559 effectively interfered the tumor growth, resulting in lighter tumor weight." (PMID 33824282, 2021). "And the content of cell cycle-related proteins (CDK1, cyclin B1 and cyclinD1) in LINC01559-silenced H1299 cells was also significantly reduced, indicating that knockdown of LINC01559 blocked the cycle of tumor cells." (PMID 34823534, 2021). "The results from this model suggested that the silencing of LINC01559 expression induced slower growth of tumors and that the tumor volumes were significantly smaller than those in the control group." (PMID 32678071, 2020). "As a result, LINC01559 suppression hampered the growth of tumor while overexpression of LINC01559 had the opposite effects." (PMID 32895368, 2020). "These pioneering studies implied that LINC01559 might have the different functions in tumor specificity." (PMID 35541914, 2022). "We then investigated the role of LINC01559 in tumor migration." (PMID 34823534, 2021). "Besides, LINC01559 silencing inhibited tumor growth in vivo." (PMID 33824282, 2021). "Moreover, we found that the expression of LINC01559 was significantly increased in both serum and tumor tissues of PC patients, indicating that LINC01559 could serve as a diagnostic biomarker." (PMID 33384999, 2020). "Further investigation revealed that macrophages upregulate the expression of the long noncoding RNA, Linc01559, in DA through the STAT3/c-MYC signaling pathway, thereby promoting malignant phenotypes such as invasion, metastasis, tumor stemness, and apoptosis." (PMID 40722682, 2025). "Functional experiments were performed to verify the relationship between Linc01559, G-rich sequence binding factor 1 (GRSF1), and tumor malignant phenotype." (PMID 40722682, 2025). "In a previous study, a myriad of evidence has demonstrated the crucial roles of LINC01559 and ARNT2 in carcinogenesis and tumor progression." (PMID 34124046, 2021).
cancer (6 papers, 2021 to 2025). A tumor composed of atypical neoplastic, often pleomorphic cells that invade other tissues. "It has been shown that LINC01559 plays a cancer-promoting role in gastric cancer and can promote the progression of pancreatic cancer via enhancing autophagy." (PMID 34823534, 2021). "Consistent with this notion, genetic silencing of LINC01559 or UNC5B-AS1 led to transcriptional misregulation in cancer." (PMID 33390837, 2021). "In conclusion, LINC01559 can enhance the autophagy of LUAD cells to exert its cancer-promoting properties." (PMID 34823534, 2021). "Among these lncRNAs, LINC00462, LINC01224, LINC00668, and LINC01559 have been demonstrated to affect the prognosis and pathogenesis of cancer." (PMID 33622186, 2021). "However, high LINC01559 expression appeared to be associated with higher histological grade (grade III-IV) and late-stage [American joint committee on cancer (AJCC) stage III-IV] of LUAD." (PMID 38311781, 2024). "Our results demonstrating that LINC01559 promotes LUAD cell migration, invasion, and metastasis not only shed new lights on the molecular mechanisms responsible for regulating the progression of LUAD, but also uncovered a novel means through which LINC01559 contributes to cancer pathogenesis." (PMID 38311781, 2024). "Similarly, whether LINC01559 regulates vimentin ubiquitination in other types of cancers and whether LINC01559 regulate ubiquitination of other proteins remain open questions." (PMID 38311781, 2024). "KEGG enrichment analysis of differentially expressed showed that LINC01559 or UNC5B-AS1 knockdown contributed to alterations in several signaling pathways, such as TNF signaling pathway, IL-17 signaling pathway, and transcriptional misregulation in cancer." (PMID 33390837, 2021).
LINC01559 also shares sentences with these, for which no sentence is quoted: renal cell carcinoma (2 papers); breast carcinoma (1); gastrointestinal tumors (1); Intellectual disability (1); liver cancer (1); papillary thyroid cancer (1); stomach adenocarcinoma (1); triple-negative breast carcinoma (1).